PFKFB3 (6-phosphofructo-2-kinase/fructose-2,6-biphosphatase 3)
Diseases named in the same sentence as PFKFB3 in open-access papers (continued):
Sharing a sentence is not in itself a finding about the gene and the disease.
ovarian carcinoma (continued). "There results indicated high expression of PFKFB3 in CSC-enriched subsets derived from ascites in ovarian cancer." (PMID 35155224, 2022). "Together, our results indicated that PFKFB3 regulates CSC properties in ovarian cancer, possibly through the NF-κB signaling pathway." (PMID 35155224, 2022). "We recently reported that activated PFKFB3 levels are high in ovarian cancer and malignant pleural mesothelioma." (PMID 33420377, 2021). "Lastly, we validated our findings regarding the importance of PFKFB3 activity for functional FA repair in ex vivo cultures established from ovarian cancer patients." (PMID 34298817, 2021). "Consistent with the results in ovarian cancer, we found in our study that both autophagy and apoptosis were increased following PFKFB3 inhibition in EC." (PMID 33420377, 2021). "In combination with either cisplatin or paclitaxel, 3PO (a novel PFKFB3 inhibitor) enhanced the cytotoxic effect in both platinum sensitive and platinum resistant ovarian cancer cells." (PMID 29866066, 2018). "We observed that the PFKFB3 inhibitor 3PO significantly enhanced the cytotoxic effect of cisplatin against both platinum sensitive and platinum resistant ovarian cancer cells." (PMID 29866066, 2018). "To investigate the importance of the PFKFB family during mitotic arrest, we examined the effects of siRNA-targeted depletion of PFKFB3 on paclitaxel treated ovarian cancer cells." (PMID 28152500, 2017). "Of all the PFKFB family members, PFKFB3 has been the most intensively studied and is overexpressed in many human cancers, including ovarian cancer." (PMID 28152500, 2017). "Firstly, the clinical significance of PFKFB3 in ovarian cancer was assessed." (PMID 35155224, 2022). "Next, we studied the role of PFKFB3 in regulating CSCs in ovarian cancer." (PMID 35155224, 2022). "Moreover, our evidence suggests the therapeutic potential of PFK158 as an inhibitor of PFKFB3 in targeting ovarian cancer." (PMID 35155224, 2022). "Moreover, Real-time PCR (qPCR) revealed up-regulation of PFKFB3 in ovarian cancer cell lines (SKOV3, OVCAR3 and TOV112D) compared with the HOSE 11-12 cell line." (PMID 35155224, 2022). "TMA analysis was used to study the expression of PFKFB3 in ovarian cancer tissues." (PMID 35155224, 2022). "However, the role of PFKFB3 in tumorigenesis, CSCs regulation of ovarian cancer, remains to be further elucidated." (PMID 35155224, 2022). "However, in ovarian cancer cells, PFKFB3 inhibition has been reported to lead to autophagy induction and chemosensitivity." (PMID 33420377, 2021). "PFKFB3 overexpression has been documented in several tumour types including ovarian cancers." (PMID 29866066, 2018). "Studies have shown that PFKFB3 is upregulated in a variety of cancers, and PFKFB3 overexpression can enhance glycolysis in ovarian cancer cells, increase lactate production, and reduce cellular oxygen consumption, supporting tumor growth, chemoresistance, metastasis and stemness in ovarian cancer." (PMID 39609317, 2024). "Moreover, higher expression of PFKFB3 decreased the survival rate and correlated with metastasis, thus, suggesting that PFKFB3 may be a novel prognostic marker for ovarian cancer." (PMID 35155224, 2022). "Mounting evidence has shown that PFKFB3 expression is significantly higher in many cancers, including high-grade astrocytoma, head and neck squamous cell carcinoma, hepatocellular carcinoma, malignant pleural mesothelioma, breast and colon, gastric, thyroid, and ovarian cancer." (PMID 33420377, 2021). "To study the role of PFKFB3 in altered CSC metabolism in ovarian cancer, we performed metabolic assays using tumorspheres/ALDH+CD44+ cells transfected with siPFKFB3 duplexes and ALDH-CD44- cells transfected with PFKFB3." (PMID 35155224, 2022). "Thus, PFKFB3 might be used as a potential therapeutic target in treating ovarian cancer." (PMID 35155224, 2022).
ovarian carcinoma (continued). "In a previous study from our group, we found that inhibition of PFKFB3 with PFK158 promotes lipophagy and autophagy and, importantly, enhances the efficacy of conventional chemotherapy in ovarian cancer." (PMID 33420377, 2021). "While numerous studies have identified the importance of PFKFB3 and PFKFB4 in cancer cell survival, we are the first to investigate the impact of their depletion in ovarian cancer cells and identify their importance during mitotic arrest." (PMID 28152500, 2017). "This work has uncovered a novel function of the enzymes PFKFB3 and PFKFB4 in ovarian cancer cells during mitotic arrest." (PMID 28152500, 2017). "PFKFB3 could induce lactate production, chemoresistance, CSC properties and tumor growth in ovarian cancer through inhibition of apoptosis and NF-κB signaling pathway." (PMID 35155224, 2022). "Our study not only found upregulated PFKFB3 in CSC-enriched ovarian cancer cells, but also revealed that PFKFB3 promoted clonogenicity and sphere-formation, and induced KLF4 and BMI1 expression in ovarian cancer cells." (PMID 35155224, 2022). "Moreover, we have identified a previously unrecognised role of PFKFB3 and PFKFB4 in mitotically arrested ovarian cancer cell survival." (PMID 28152500, 2017). "This discrepancy might be due to PFKFB3 and PFKFB4 having distinct roles in ovarian cancer cells." (PMID 28152500, 2017). "In this study, inhibition of five glycolysis pathway molecules (GLUT1, HKII, PFKFB3, PDHK1 and LDH) using 9 inhibitors (Phloretin, Quercetin, STF31, WZB117, 3PO, 3-bromopyruvate, Dichloroacetate, Oxamic acid, NHI-1) was investigated in panels of breast and ovarian cancer cell line models." (PMID 26259240, 2015). "Here, we isolated tumorspheres or an ALDH+CD44+ cell subset from ascites or ascites-originating ovarian cancer cell lines (SKOV3 and OVCAR3) and compared the PFKFB3 expression between the CSC-enriched subpopulation and non-CSCs." (PMID 35155224, 2022). "Our findings of decreased PFKFB3 protein expression in A2780S cells but not in A2780CP cells after cisplatin treatment, suggesting a differential regulation of PFKFB3 expression between sensitive and resistant ovarian cancer cells by cisplatin treatment." (PMID 35155224, 2022).
pancreatic cancer (15 papers, 2015 to 2025). "The knockdown of PFKFB3 reduces Snail expression and upregulates E-cadherin levels in pancreatic cancer cells." (PMID 37919747, 2023). "Consistently, the PFKFB3-Ser172 phosphorylation level inversely correlated with the OGT level in pancreatic cancer patients." (PMID 32060258, 2020). "To determine the clinical relevance of our finding that OGT inhibits hypoxia-induced PFKFB3-S172 phosphorylation, we performed IHC to analyze OGT and PFKFB3 pSer172 levels in 73 human pancreatic tumor specimens with validation of the antibody." (PMID 32060258, 2020). "Bobarykina and colleagues showed that the PFKFB3 gene was expressed in gastric and pancreatic cancer cells and responded strongly to hypoxia via an HIF-1α dependent mechanism." (PMID 26337471, 2015). "Furthermore, it was demonstrated that PFKFB3 siRNA transfection reduced Snail expression and simultaneously upregulated E-cadherin levels in pancreatic cancer cells." (PMID 33671514, 2021). "In pancreatic cancer, p38γ binds phosphofructokinase-2/fructose-2,6-bisphosphatase 3 (PFKFB3) in KRAS-transformed cells and phosphorylates PFKFB3 at S467 in human pancreatic cancer cells and in mouse KPC tumors." (PMID 37443708, 2023). "p38γ KO reduced PFKFB3 phosphorylation, PFKFB3 and GLUT2 protein expression, and inhibited aerobic glycolysis to impede pancreatic cancer cell growth." (PMID 35246508, 2022).
pulmonary fibrosis (15 papers, 2018 to 2025). Chronic progressive interstitial lung disorder characterized by the replacement of the lung tissue by connective tissue, leading to progressive dyspnea, respiratory failure, or right heart failure. "In addition, some drugs have been reported to inhibit pulmonary fibrosis by interfering with PFKFB3‐associated glycolysis." (PMID 37199341, 2023). "Another study revealed that lung fibroblasts displayed augmented aerobic glycolysis through activation of the PI3K-Akt-mTOR/PFKFB3 pathway in LPS-induced pulmonary fibrosis." (PMID 34603058, 2021). "A previous study demonstrated that LPS activates the PI3K-Akt-mTOR/PFKFB3 pathway, and promotes the collagen synthesis of lung fibroblasts through aerobic glycolysis to aggravate pulmonary fibrosis." (PMID 33777519, 2021). "To determine the functional impact of PCBP3-mediated regulation of PFKFB3 expression in lung fibrosis, we transfected lung fibroblasts with FLAG-PCBP3." (PMID 34603058, 2021). "Lipopolysaccharide promotes aerobic glycolysis in pulmonary fibroblasts by activating the PI3K-Akt-mTOR/6-phosphofructo-2-kinase/fructose-2,6-biphosphatase 3 (PFKFB3) signaling pathway, which promotes collagen synthesis in pulmonary fibroblasts and contributes to pulmonary fibrosis." (PMID 39465434, 2024). "Additionally, in fibroblast foci in lung epithelial cells, macrophages, and IPF lungs, as well as in experimental models of pulmonary fibrosis, there was an increase in 6-phosphofructo-2-kinase/fructose-2,6-bisphosphatase 3 (PFKFB3)." (PMID 39175820, 2024). "The role of PFKFB3 in fibrosis was primarily explored in an experimental model of pulmonary fibrosis, in which PFKFB3 knockdown and an inhibitor suppressed the fibrotic activity of lung myofibroblasts and lung fibrosis in a mouse model." (PMID 37626891, 2023). "In 2022, the team also revealed that LPS-induced macrophage secretion of TNF-α could initiate fibroblast PFKFB3-driven aerobic glycolysis, which plays an essential role in LPS-induced pulmonary fibrosis." (PMID 37199341, 2023). "All of these findings indicate that targeting PFKFB3‐driven glycolysis in lung fibroblasts might be a promising therapeutic approach for septic pulmonary fibrosis." (PMID 37199341, 2023). "This future direction may be important to better understand how PCBP3 regulates PFKFB3-mediated glycolysis in pulmonary fibrosis." (PMID 34603058, 2021). "Similarly, in pulmonary fibrosis, activated myofibroblasts exhibit increased expression of the glycolytic enzyme phosphofructo-2-kinase/fructose-2,6-biphosphatase 3 enzyme (PFKFB3), and use of a PFKFB3 inhibited attenuated the differentiation of lung fibroblasts into activated fibroblasts." (PMID 35328687, 2022). "However, one of the limitations of this study is that we didn’t knock out PCBP3/PFKFB3 in mice to verify their effects in lung fibrosis, which may be explored in the further research." (PMID 34603058, 2021). "Xie et. al. reported that inhibition of 6-phosphofructo-2-kinase/fructose-2,6-biphosphatase 3 (PFKFB3), a glycolytic enzyme that is upstream of LDHA, also inhibits bleomycin-induced pulmonary fibrosis." (PMID 29795645, 2018). "PFKFB3 inhibitor that blocks bleomycin- and TGF-β1-induced lung fibrosis in mice." (PMID 34859009, 2021).
rheumatoid arthritis (15 papers, 2015 to 2025). A chronic, systemic autoimmune disorder characterized by inflammation in the synovial membranes and articular surfaces. "Deficiency of PFKFB3 has been linked to reprogrammed metabolism in T cells from rheumatoid arthritis patients." (PMID 29453388, 2018). "In rheumatoid arthritis T cells, PFKFB3 deficiency restrained activation of the autophagic process, whereas PFKFB3 inhibition promoted autophagy in HCT116 cells." (PMID 29113354, 2017). "Others have described this hypoglycolytic phenomenon in other immunological diseases such as rheumatoid arthritis (RA), with deficiencies in the glycolytic enzyme phosphofructokinase (PFKFB3)." (PMID 29163546, 2017). "The initial research associating PFKFB3 and autophagy was in rheumatoid arthritis (RA), in which researchers found that T cells from RA patients failed to metabolize equal amounts of glucose as control cells, subsequently generated less intracellular ATP, and were prone to induce apoptosis." (PMID 28977989, 2017). "Initial research in patients with rheumatoid arthritis (RA) showed that lower expression levels of PFKFB3 were associated with a G6P shunt towards PPP, leading to NADPH production and ROS depletion, and, as a result, autophagy inhibition." (PMID 33671514, 2021). "We have identified that PFKFB3 is elevated in rheumatoid arthritis (RA) neutrophils and that the small molecule PFKFB3 inhibitor 3PO is a key regulator of neutrophil ROS and NET production." (PMID 39969221, 2025). "Paradoxically, PFKFB3 expression is reported to correlate with pro-invasive and pro-inflammatory activity in rheumatoid arthritis patients, while selective inhibition of endothelial PFKFB3 reduces polarization of M2 macrophages." (PMID 41235226, 2025). "In rheumatoid arthritis, there is growing evidence that synovial fibroblasts rely on high glycolysis and inhibition of PFKFB3 alleviates synovial fibroblast-mediated synovial inflammation." (PMID 36405760, 2022). "Inhibition of PFKFB3 by PFK15 has been reported to alleviate rheumatoid arthritis induced inflammation and suppress the growth of various tumors in mice." (PMID 36405760, 2022). "The 440kB region between PFKFB3 and Protein Kinase C Theta (PRKCQ) has been reported in a meta-analysis to identify rheumatoid arthritis (RA) risk loci in European populations, and also has been shown to be associated with T1D." (PMID 27015091, 2016). "In T cells derived from patients with rheumatoid arthritis, Pfkfb3 expression was reduced, glycolysis was impaired and PPP flux was increased, resulting in impaired energy generation and senescence." (PMID 26194095, 2015). "Likewise, the defective induction of PFKFB3 in T cells from rheumatoid arthritis patients was reported to drive a hypoglycolytic phenotype, impairing ATP generation, the redox balance, and the production of ROS." (PMID 34044589, 2021). "It has been reported that the inhibition of PFKFB3 promoted autophagy in HCT116 cells, while knockdown of PFKFB3 restrained the activation of autophagy in rheumatoid arthritis T cells." (PMID 29113354, 2017). "In rheumatoid arthritis, fibroblast-like synoviocytes prefer glycolysis, accompanied by a higher expression of glucose transporter 1 (GLUT1) and 6-phosphofructo-2-kinase/fructose-2, 6-bisphosphatase 3 (PFKFB3)." (PMID 36405760, 2022).
melanoma (13 papers, 2017 to 2025). A malignant, usually aggressive tumor composed of atypical, neoplastic melanocytes. "PFKFB3 expression is upregulated in tumor endothelial cells (TECs), and blocking the enzyme decreased melanoma metastasis and improved EC barrier integrity, independent of the presence of VEGFA." (PMID 39567756, 2025). "3PO reported as a selective inhibitor of 6-phosphofructo-2-kinase/fructose-2,6-biphosphatase 3 (PFKFB3) has proapoptotic and anti-proliferative role in human melanoma cells A375 with BARF V600E mutation." (PMID 32565740, 2020). "Phosphofructokinase 2/fructose 2,6-bisphosphatase 3 performs crucial roles in glycolysis and lactate production in tumor cells, and the combination inhibitor PFK-158 targets PFKFB3 with cytotoxic T lymphocyte antigen 4 and enhances therapeutic efficacy in a melanoma model." (PMID 36854755, 2023). "Altogether, these data confirmed the contribution of PFKFB2/PFKFB3 to the survival response to metabolic stress in NRASQ61 mutant melanomas, revealing a link between the RAS and glycolytic pathways, which implies the regulation of PFKFB2 by BRAF and probably ERK proteins." (PMID 36402789, 2022).
renal fibrosis (11 papers, 2023 to 2025). A final common manifestation of a wide variety of chronic kidney diseases characterized by glomerulosclerosis and tubulointerstitial fibrosis. "To investigate the role of myeloid PFKFB3 in renal fibrosis, we generated myeloid-specific Pfkfb3-deficient mice (Pfkfb3ΔMφ) and their controls (Pfkfb3WT) by breeding floxed Pfkfb3 mice with Lysm-Cre mice." (PMID 38035106, 2023). "In this study, to determine the specific role of glycolysis in myofibroblasts and renal fibrosis, we generated mice with Pfkfb3 deficiency, specifically in myofibroblasts, and challenged them with ureter obstruction or kidney ischemia to induce fibrosis." (PMID 37626891, 2023). "To investigate the role of myeloid glycolysis in renal fibrosis, we utilized a model of unilateral ureteral obstruction in mice deficient of Pfkfb3, an activator of glycolysis, in myeloid cells (Pfkfb3ΔMφ) and their wild type littermates (Pfkfb3WT)." (PMID 38035106, 2023). "Therefore, the Mettl3/Pfkfb3/lactate/H3K18la/PD-L1 pathway was a common mechanism underlying the development of both renal fibrosis and tumor growth during repeated low-dose CDDP-based cancer therapy." (PMID 40765834, 2025). "In PFKFB3-deficient myeloid cells, glycolytic metabolite levels are significantly reduced, which restricts the transition from macrophages to myofibroblasts, ultimately diminishing renal fibrosis." (PMID 41425966, 2025). "Although HIF-1 activation in renal epithelial cells has been implicated in renal fibrosis and epithelial PFKFB3 upregulation has been reported during renal fibrosis, it remains unclear whether there is fibroblast-specific HIF-1 activation that regulates PFKFB3." (PMID 37626891, 2023). "The data show that Pfkfb3, downstream gene of Mettl3, promotes the progression of renal fibrosis as well as production of production of pyruvate and lactate during repeated low-dose CDDP." (PMID 40765834, 2025). "In the current study, we discovered that Mettl3 increases the stability of Pfkfb3 via m6A modification to induce the development of renal fibrosis." (PMID 40765834, 2025). "Recently, multiple studies have identified PFKFB3 as a key contributor to the progression of renal fibrosis." (PMID 40765834, 2025). "In Pfkfb3 knockout mice, renal fibrosis‐related genes and NF‐κB inflammatory pathway‐related genes were reduced." (PMID 40984037, 2025). "PFKFB3 has been shown to increase glycolytic flow, which raises fibroblast activation and contributes to the development of renal fibrosis." (PMID 40271532, 2025). "PFKFB3 mainly localises in proximal tubular cells and is positively correlated with the severity of renal fibrosis." (PMID 40984037, 2025). "Our study indicates that HIF1α plays a significant role in the effect of PFKFB3-medaited glycolysis on phenotypic alterations observed in macrophages in renal fibrosis." (PMID 38035106, 2023). "Nevertheless, one critical glycolytic activator, 6-phosphofructo-2-kinase/fructose-2,6-bisphosphatase 3 (PFKFB3), remains unexplored in renal fibrosis." (PMID 37626891, 2023). "In conclusion, our study demonstrates the critical role of PFKFB3 in driving fibroblast activation and subsequent renal fibrosis." (PMID 37626891, 2023). "Despite this, we observed significant suppression of renal fibrosis by Pfkfb3 knockout, indicating that the later stage of scarring was effectively suppressed." (PMID 37626891, 2023). "This discovery of the new role of PFKFB3 also provides a potential therapeutic target for the treatment of renal fibrosis." (PMID 37626891, 2023). "Combined with in vitro assays to examine PFKFB3 knockdown and inhibition in renal fibroblasts, we elucidated the pro-fibrotic role of PFKFB3 in myofibroblasts and its role through downstream glycolysis regulation in renal fibrosis." (PMID 37626891, 2023). "The role of PFKFB3-mediated glycolysis in myeloid cells in renal fibrosis aligns with its role in myeloid cells in pathological angiogenesis." (PMID 38035106, 2023).